DNMT3B (DNA methyltransferase 3 beta)
Diseases named in the same sentence as DNMT3B in open-access papers (continued):
Sharing a sentence is not in itself a finding about the gene and the disease.
cancer (318 papers, 2005 to 2026). A tumor composed of atypical neoplastic, often pleomorphic cells that invade other tissues. "In contrast, Single-Nucleotide Polymorphisms (SNPs) in DNMT3B promoters alter their expression in cancer." (PMID 41226543, 2025). "The overexpression of DNMT3B is common to many cancers and has been associated with poor clinical outcomes in hepatocellular carcinoma, oral cancer, esophageal carcinoma, and triple-negative breast cancer." (PMID 38157850, 2024). "DNMT3A and DNMT3B mutations cause human Mendelian disorders and somatic driver mutations are reported in cancer." (PMID 39446312, 2024). "Putative DNMT3A and DNMT3B somatic driver mutations are also widespread in cancer but the majority of these are uncharacterised with the exception of DNMT3A mutations in acute myeloid leukeamia (AML)." (PMID 39446312, 2024). "In our analysis, both maintenance methylation (DNMT1, DNMT2) and de novo methylation (DNMT3a, DNMT3b) were found to be significantly associated with pan-cancer, resulting in the methylation of CEP55 at positions cg25827255, cg25314624, and cg04026927." (PMID 37887301, 2023). "Thereby, in this review, we compiled literature on ncRNAs associated with DNMT3B in human cancer, along with the potential underlying mechanisms linking them, which play a role in all stages of human cancer." (PMID 37705098, 2023). "Accumulating evidence has provided significant support for the involvement of DNA hypermethylation/hypomethylation, dysregulation of DNMT3B, and chromatin remodeling in the processes underlying cancer initiation, and development." (PMID 37705098, 2023). "The study disclosed that overexpressing DNMT3B in HaCaT cells resulted in the modulation of genes associated with cancer." (PMID 37705098, 2023). "In this manner, these findings indicated that DNMT3B dysregulation is linked to cancer development and progression." (PMID 37705098, 2023). "The mRNAs and proteins that encode DNMTs (DNMT1, DNMT3A, and DNMT3B) with their related catalytic activities are overexpressed in different cancer types, leading to aberrant behavior compared with normal cells." (PMID 37107631, 2023). "In the next section, we will review the knowledge of each DNMT3B isoforms, its associated function, and studies that prove the importance of isoforms expression, mainly by pluripotent stem cells and cancer cells." (PMID 36012258, 2022). "CGIs hypermethylation associated with DNMT3B has been found to increase in cancer and consequently, the methylation of genes with CGI is enhanced." (PMID 36460706, 2022). "Overexpression of each DNMT3B isoform has been associated with any cancer initiation, development, progression, or metastasis." (PMID 36012258, 2022). "To highlight the general findings associated with the DNMT3B overexpression that involves several genes and key pathways, we select a common biological process de-regulated in cancer, cell migration." (PMID 36460706, 2022). "The survival analysis results from Kaplan–Meier plots depicted the association between DNMT3B levels expression and cancer prognosis; high DNMT3B expression in representative tumors is significantly associated with poor prognosis." (PMID 36460706, 2022). "DNMT3B is the methyltransferase most often implicated in the aberrant methylation of CGIs in cancer." (PMID 33514701, 2021). "It is reasonable to assert that the DNMT3B polymorphism is associated with cancer development by increasing the promoter activity of DNMT3B and modulating an aberrant de novo methylation of CpG islands in some TSG." (PMID 34587932, 2021). "Among genes associated with DNMT3B-reduced peaks within gene regulatory regions, we found strong candidates associated with inhibition of cancer proliferation, migration, and metastasis, and activation of apoptosis." (PMID 34439480, 2021).
cancer (continued). "In human cells, satellite DNA overexpression is observed during stress, senescence, aging, and in various cancers associated with deregulation of epigenetic enzyme activities (e.g., DNMT3B, KDM2A, JMJD2B, SIRT6, GCN5, BRCA1, PRC1, and PRC2)." (PMID 34681626, 2021). "Given their functions in both the establishment and maintenance of genomic DNA methylation DNMT3A and DNMT3B critically contribute to the aberrant cancer-associated methylation patterns." (PMID 32806509, 2020). "Previous studies found that cancer cells express aberrant DNMT3B transcripts encoding truncated proteins which are hypermethylated, and transcriptionally inactivate tumor suppressor genes." (PMID 33233545, 2020). "DNMT3B is involved in cancer stemness maintenance and is closely associated with cancer proliferation and metastasis." (PMID 32065219, 2020). "In carcinoma-associated fibroblasts, DNMT3B methylated CpG sites of the promoter of SHP-1 phosphatase and abrogated SHP-1 expression, leading to constitutive phosphorylation of JAK1." (PMID 32895373, 2020). "The findings of these investigations suggested that the DNMT3B-579T allele was associated with an increased risk of cancer." (PMID 31565203, 2019). "High expression of DNMT3A or DNMT3B has been observed in a large number of specimens from cancer patients, and increased DNMT3A expression is implicated in hepatocellular carcinogenesis." (PMID 31615043, 2019). "Here in this study, we present the first mechanistic evidence of curcumin causing the switch in the PKM splicing from cancer-specific PKM2-isoform to normal PKM1-isoform by inhibiting the DNMT3B in HNC cells." (PMID 31675998, 2019). "Based on meta-analysis data, a polymorphism in a DNMT3B regulative region has also been associated with reduced risk of cancer but this point is still debated." (PMID 30406101, 2018). "Cancer cells have many aberrant transcripts of DNMT3B, which is linked to E-cadherin promoter gene methylation and CRC aggressiveness." (PMID 30405408, 2018). "De novo DNA methylation activity, catalyzed by DNMT3A and DNMT3B, is essential during embryonic development or gametogenesis but is also frequently associated to aberrant gene repression in many pathologies (e.g., cancer)." (PMID 29449903, 2018). "Some other SNPs of DNMT3B, such as −579 G/T and −283 T/C, were also researched by some studies on their association with cancer risk." (PMID 25433949, 2015). "More studies are needed to detect DNMT3B −149C/T polymorphism and its association with cancer in different ethnic populations incorporated with environment exposures in the susceptibility of different kinds of cancer." (PMID 25433949, 2015). "These SNPs were found to affect the activity of DNMT3b on DNA methylation by changing the level of DNMT3b, thereby modulating the susceptibility to cancer." (PMID 26262893, 2015). "Here, we performed a meta-analysis on 22 published case–controls to derive a more precise evaluation of the association between DNMT3B −149C/T polymorphism and cancer risk." (PMID 25433949, 2015). "Several previous studies have shown that polymorphisms of DNMT3b are associated with cancer development in a variety of tumors." (PMID 26262893, 2015). "Recently, a variety of molecular epidemiological studies have been conducted to examine the association between DNMT3B −149C/T polymorphism and cancer susceptibility, but the results remain inconclusive." (PMID 25433949, 2015). "Numbers of SNPs, however, were frequently investigated in the former studies to evaluate the association between DNMT3B polymorphisms and cancer in diverse populations." (PMID 25433949, 2015). "More recently, splice variants of DNMT3B transcripts have been detected in a wide range of cancer cell lines." (PMID 25198254, 2014). "The results of other investigations regarding the association between DNMT3B single nucleotide polymorphism (SNPs) and the risk of cancer were conflicting." (PMID 24850984, 2014).
cancer (continued). "With the exceptions of DNMT3B, which is significantly overexpressed in most cancer types studied here, and DNMT3A which is highly mutated in LAML, we do not see notable mutation rates or cancer-associated changes in expression level for DNMTs and HDACs." (PMID 25484917, 2014). "Present data are in agreement with a literature meta-analysis suggesting an increased risk of cancer associated with the presence of the DNMT3B-579T allele." (PMID 24260492, 2013). "Cellular DNA methylation is orchestrated by three distinct DNA methyltransferases, DNMT1, DNMT3a and DNMT3b, and aberrant expression of these DNMTs has been causally linked to atypical DNA methylation levels in human cancers." (PMID 24252647, 2013). "In cancer cells loss of Dnmtase activity and suppression of Dnmt1 and Dnmt3b lead to passive loss of global hypomethylation during rapid proliferation." (PMID 22905112, 2012). "Although some researchers have found that DNMT3b variants have diverse expression profiles in cancer tissues, the research on these variants and their function is very limited." (PMID 22457770, 2012). "Future studies of other DNMT3B sequence variants and their biologic function are also needed to understand the role of DNMT3B polymorphisms in determining the risk of cancer." (PMID 18662374, 2008). "This study examines the expression levels of certain proteins (DNMT1, DNMT3A, and DNMT3B) in tumor tissue, using immunohistochemistry to assess whether these protein levels are linked to the risk of cancer recurrence or mortality." (PMID 40507223, 2025). "Specifically, DNMT3B is associated with abnormal methylation of cancer-related genes." (PMID 40140215, 2025). "In conclusion, we report of an unexpected consequence of DNMT3B PWWP mutations which reveal that DNMT3B plays a role in DNA methylation homoeostasis at heterochromatin, a genomic compartment whose DNA methylation levels are frequently altered in cancer and other human diseases." (PMID 38291337, 2024). "Mutations in DNMT3A and DNMT3B cause rare Mendelian diseases in humans and are cancer drivers." (PMID 39446312, 2024). "DNMT3B mRNA expression has been recently associated with increased cancer aggressiveness." (PMID 38368287, 2024). "Thus, as with ATRX mutation in ALT cancer cells and DNMT3B mutation in ICF syndrome type I fibroblasts, MLL rearrangements in MLL-r ALL would also appear to prevent a negative feedback regulation of TERRA." (PMID 36979904, 2023). "In addition, a close relationship was observed between PLOD2 expression and mutations in 4 methyltransferases (DNMT1, DNMT2, DNMT3A, DNMT3B) in several cancer types." (PMID 35586565, 2022). "However, correlation analyses between DNMT3B − 149 polymorphism and specific cancers seldom take into account the effect of environmental factors." (PMID 34587932, 2021). "DNMT3B gene mutation was generally higher expression level among various cancers." (PMID 34325709, 2021). "However, studies on the association between smoking-related cancers and epigenomic alterations showed that cigarette smoke influenced DNMT3B gene expression, thus changing DNA methylation patterns." (PMID 32118373, 2020). "According to different meta-analyses, DNMT3B-579G>T might involve in the susceptibility to cancers, especially in Asian populations." (PMID 31565203, 2019). "Therefore, it was suggested that the DNMT3B -149C>T polymorphism increases human cancer risk by increasing DNMT3B gene expression levels resulting in increased promoter methylation and silencing of tumor suppressor genes." (PMID 31370354, 2019). "Indeed, the contribution of DNMT3B polymorphisms to human disease has been investigated in many other diseases than cancer." (PMID 31370354, 2019). "Various studies have provided evidence for the association of DNMT3B polymorphisms with cancers." (PMID 31565203, 2019). "Genetic mutations in DNMT3B locus are observed with low frequency also in cancer." (PMID 30406101, 2018).
cancer (continued). "Therefore, de novo methyltransferase DNMT3b is implicated in the establishment of gene-specific hypermethylation during cancer development and progression." (PMID 29290961, 2017). "Future research will investigate whether drugs that inhibit the breakdown of fats could help to treat cancers in which the Dnmt3a and Dnmt3b proteins are mutated or less active." (PMID 28425913, 2017). "Larger samples among different populations, especially more sophisticated gene–gene and gene–environment interactions should be considered in future studies, which should lead to better, comprehensive understanding of the association between DNMT3B −149C/T polymorphism and cancer risk." (PMID 25433949, 2015). "Given the important roles of DNMT3B in cancer risk, it was biologically possible that DNMT3B polymorphism is associated with the risk of cancer by increasing DNMT3B promoter activity that modulated an aberrant de novo methylation of CpG islands in some tumor suppressor genes." (PMID 25433949, 2015). "Therefore, the association between DNMT3B −149C/T polymorphism and cancer risk requires further investigation." (PMID 25433949, 2015). "Moreover, DNMT3B promoter polymorphisms have been associated with global DNA methylation and are increasingly investigated in other complex diseases than cancer." (PMID 24260492, 2013). "In addition, overexpression of either DNMT3A or DNMT3B is associated with tumorigenesis depending on cancer types in humans." (PMID 23613894, 2013). "This is consistent with the recent observation that hypomethylation in gastric CAFs could not be attributed to any difference in mRNA levels of DNMT1, DNMT3a, or DNMT3b between normal and cancer-associated myofibroblasts." (PMID 22984426, 2012). "Among these three enzymes, upregulation of DNMT3b is a characteristic of many cancer cells, and DNMT3b may play a causal role in tumorigenesis." (PMID 22808286, 2012). "The DNMT3B gene encodes a DNA methyltransferase enzyme that is localized to the nucleus, developmentally regulated, and functions to establish de novo methylation patterns; DNMT3B expression is associated with cancer." (PMID 22103680, 2011). "A novel DNMT3B splice variant was found to be expressed in pluripotent and cancer cells." (PMID 21496241, 2011). "Gain at 8q, resulting in amplification of the oncogene c-Myc, was also consistently identified, as was gain at chromosome 20, a specific marker of HPV-associated cancer that has been reported to result in elevated mRNA levels of the de novo DNA methyltransferase DNMT3B at 20q." (PMID 20234371, 2010). "Polymorphisms of the DNMT3B gene may influence DNMT3B activity on DNA methylation in several cancers, thereby modulating the susceptibility to cancer." (PMID 18662374, 2008). "Polymorphism of the DNMT3b gene may influence DNMT3b activity and be associated with cancer risk." (PMID 26262893, 2015). "There might be some other SNPs in DNMT3B associated with risk of cancer." (PMID 25433949, 2015). "Indeed immunohistochemical findings in specimens from in vivo xenografts suggested a specific involvement of DNMT3b inhibition exerted by the low dose 5-Aza-2′-dC-loaded EMHVs (120 ng) in presence of magnetic field causing apoptotic response on target cancer cells." (PMID 24851905, 2014). "Likewise, our work illustrates how overexpression of inactive DNMT3B variants may lead to the generation of aberrant DNA methylation patterns in diseases such as cancer." (PMID 23894490, 2013). "Taken overall, results from those studies coupled with the evidence of an association of the DNMT3B-579G>T polymorphism with various types of cancer, suggest that this polymorphism might either have a functional role on gene expression levels, or be a tag SNP of functional haplotypes." (PMID 24260492, 2013).
cancer (continued). "The observed resistance to demethylation at these loci could be explained by redundant activities in the establishment and maintenance of DNA methylation by DNMT3A and DNMT1, respectively, being capable of activity compensating for the loss of DNMT3B in human cancer cells in vitro." (PMID 22563479, 2012). "Specifically, CUL4A preferentially binds to DNA methyltransferase 3b (DNMT3b) via its C terminus in a neddylation-dependent manner, therefore promoting DNMT3b-mediated DNA methylation in cancer cells." (PMID 41540013, 2026). "High DNMT3B expression is associated with silencing of tumor suppressor genes, such as E-cadherin (CDH1), the promotion of EMT, the maintenance of cancer stemness, and chemoresistance." (PMID 41596471, 2026). "Many nucleoside and non-nucleoside inhibitors are validated to target several DNMTs, including DNMT3B in various cancers." (PMID 41596471, 2026). "DNMTs (DNMT1, DNMT3A and DNMT3B) upregulation is promoted by oncoproteins E6 and E7 and the magnitude of their expression is directly related to cancer progression in CC." (PMID 40159638, 2025). "Specifically, STAT3 phosphorylation has been found to increase DNMT1, DNMT3A, and DNMT3B expression in cancer cells." (PMID 40427627, 2025). "In inherited diseases and cancers, several reports suggest that DNMT3B are regulated at transcriptional and post-translational levels." (PMID 40595027, 2025). "Evidence has shown that the PI3K/AKT pathway mediates epigenetic regulation in cancer through DNMT1 and DNMT3B stabilization and upregulation in cancers such as glioblastoma and leukemia." (PMID 40427627, 2025). "The results indicated that USP37 was significantly associated with at least one of the four methyltransferase genes (DNMT1, DNMT2, DNMT3A, and DNMT3B) in various cancer types, except UCS." (PMID 40926837, 2025). "In laboratory settings, DNC has been shown to reactivate the expression of miR-34s by inhibiting DNMT1, DNMT3A, and DNMT3B in HepG2 and Huh7 cell lines, reducing the viability of these cancer cells." (PMID 39829957, 2025). "Similar to our results, DNMT3b has been observed to be excessively expressed in many types of cancer, contributing to tumor growth and metastasis." (PMID 41602133, 2025). "NA is a quinone antibiotics that selectively targets DNMT3B by directly interacting with its catalytic site, thereby reducing global DNA methylation and inducing cytotoxicity in several cancer cell lines." (PMID 40241199, 2025). "DNMT1 and DNMT2 are positively correlated with most cancers, while DNMT3A and DNMT3B are inversely correlated with most cancers." (PMID 38166842, 2024). "The PI3K/Akt pathway participates in the mediation of DNMT3B expression in some cancers, but its role in TMZ resistance in GBM cells has rarely been reported." (PMID 38368287, 2024). "Further analyses revealed that RAB42 overexpression is positively correlated with writer genes TRMT10C, TRMT61B and reader gene DNMT3B in most cancers." (PMID 39101146, 2024). "The study elucidated that EGCG attenuates DNMT activity and protein levels, encompassing DNMT1, DNMT3a, and DNMT3b, reinstates tumor suppressor genes, and diminishes cell proliferation, thereby offering a multifaceted approach to cancer treatment." (PMID 38879474, 2024). "Our results here and those of our previous study of CpG islands suggest that, similarly to normal cells, the majority of DNMT3B in cancer cells localises and is active at H3K36me3-marked regions." (PMID 38291337, 2024). "Many other DNMT3B isoforms have been reported to be expressed in cancers but are poorly characterised, making their functional impact and expression levels unclear." (PMID 39446312, 2024). "DNMT3B, a de novo methyltransferase, is highly expressed and frequently upregulated in many malignant tumors." (PMID 38368287, 2024).